CD44 (CD44 molecule (IN blood group))
Diseases named in the same sentence as CD44 in open-access papers (continued):
Sharing a sentence is not in itself a finding about the gene and the disease.
breast carcinoma (continued). "Al-Hajj's research in 2003 has shown that breast cancer stem cells (ESA+CD44+CD24-/low, BCSCs) possessing the stem cell properties of self-renewal and multi-directional differentiation are the most fundamental contributors to drug resistance, recurrence and metastasis of breast cancer." (PMID 21192833, 2010). "Due to the well-characterized dominant effect of CD44 on cell behavior and the fact that previous work has compared CD44dim/neg to CD44pos cells, the regulation of CD24 and its specific role in breast cancer cell behavior is largely unknown." (PMID 19906290, 2009). "It has been reported that use of the surface marker CD133 can isolate a group of breast cancer stem cells that does not overlap with CD44+/CD24− cells, which is consistent with our data that CD44+/CD24− cells may not have the highest tumorigenic ability." (PMID 20027313, 2009). "This phenotype seems to be conserved during the carcinogenesis process and thus is an important tool to study breast cancer progression, however, it is limited by the great cellular heterogeneity of the CD44+/CD24-/low/lin-population, which probably does not contain solely bona fide CSCs." (PMID 19555472, 2009). "Interestingly, P245 mAb does not block HA binding to mammary tumour cells (data not shown), indicating that P245 and HA bind distinct regions of the CD44 protein." (PMID 19240712, 2009). "Furthermore, early cancer cells detected in bone marrow of breast cancer patients were observed to have breast cancer stem sell phenotype, but the frequency of CD44+/CD24-/low cells in breast cancer tissue was not correlated with clinical outcome." (PMID 18433506, 2008). "Additionally, the CD44+CD24− cells contain a molecular signature originally identified in breast tumorigenic cells that can predict patient outcome not only in breast cancer but also in prostate cancer." (PMID 18268494, 2008). "Since there was a clear correlation between the CD44+/CD24- status and the basal-like tumor subtype, we extended the immunohistochemical analysis to an additional TMA including tumors from BRCA1 hereditary breast cancer patients, known to be of predominantly basal-like phenotype." (PMID 18559090, 2008). "We found that the CD44+/CD24- status was associated with low/negative HER2 expression and with elevated expression of CK5/14 and EGFR, as well as with medullary histological type, all known characteristics of the basal-like subtype of breast cancer." (PMID 18559090, 2008). "In addition, the lack of enrichment in the putative mammary cancer stem cell surface phenotype, CD44+/CD24−, in the single-step doxorubicin-selected MCF-7 clones further supports the theory of adaptation over selection with these studies." (PMID 18382425, 2008). "In the luminal type of breast cancer cell line MCF-7, the overexpression of SLUG created cells with a CD44+/CD24+ phenotype, suggesting that basal cell types and not luminal types are more susceptible to acquisition of CD44+/CD24− phenotype, which is associated with EMT." (PMID 38398019, 2024). "Thus, we fabricated a CD44-targeting and tumor microenvironment pH/redox-sensitive nanosystem composed of hyaluronic acid-vitamin E succinate and poly (β-amino esters) (PBAEss) polymers to enhance the TPL-mediated suppression of breast cancer proliferation and lung metastasis." (PMID 34162396, 2021). "As there exists two distinct populations of CSCs in breast cancer, when reviewing the literature for the potential role of prostaglandin signaling in breast CSC phenotypes it is important to define how the CSCs were identified since there may be a CD44+/CD24- or ALDH+ specific effect." (PMID 35127497, 2021). "To investigate whether lncRNAs involved in regulating breast cancer stem cell characteristics, we utilized microarray analysis to compare lncRNA expression profiles between non-BCSCs (CD44−/lowCD24+ cells) and BCSCs (CD44+CD24−/low mammospheres) from MCF7 cells." (PMID 34715882, 2021).
breast carcinoma (continued). "However, the proportion of ALDH+ cells (epithelial-like BCSCs, E-BCSCs) was increased and the proportion of CD44+ CD24− cells (mesenchyme-like BCSCs, M-BCSCs) was decreased after LDHA silencing, suggesting a regulatory role of LDHA in E-BCSCs/M-BCSCs transformation in mouse breast cancer cells." (PMID 34178639, 2021). "In addition, interestingly, we found a higher population of CD24−/low/CD44+ cells among RT-R-TNBC cells than among TNBC cells, and RT-R-TNBC cells showed more aggressive tumorigenic properties related to tumor cell growth, migration and invasion than the parental breast cancer cells." (PMID 34502547, 2021). "However, CD44 overexpression only slightly mitigated the levels of proapoptotic proteins BID and BAX, which were increased in MARCH8-GFP-overexpressing cells, suggesting that additional targets of MARCH8 are responsible for the alteration of proapoptotic signals in breast cancer cells." (PMID 34067416, 2021). "Indeed, several analyses of human breast carcinomas have revealed TNBCs harbor the highest percentage of CD44+CD24-ALDH1+CSCs, a feature that usually correlates negatively with chemotherapy response, disease-free survival, metastasis-free survival, and overall survival." (PMID 35582030, 2021). "Additionally, among splicing regulators frequently altered in breast cancers (in >5% of tumors), we found different members of SR protein family (such as SRSF1, SRSF2, SRSF3, SRSF4, SRSF6, SRSF9, SRSF10, SRSF11) with at least one predicted binding motif in the CD44 v10 region." (PMID 33143085, 2020). "However, the later published evidence that the two breast cancer CSC populations (i.e., ALDH+ and CD24−/CD44+) investigated reside in different areas of primary breast tumors and can transition from one phenotype to the other might affect the reliability of CSC counts in this patient population." (PMID 30788286, 2019). "Finally, we have previously observed that breast cancer cells with high ALDH activity and CD44 expression (ALDHhiCD44+ phenotype) are significantly more resistant to chemotherapy and radiation therapy, and that this therapy resistance may occur, at least in part, via ALDH1-dependent mechanisms." (PMID 28937653, 2017). "In addition, CD74 interacts with CD44 which is highly expressed in breast cancer stem cells (CSC), hinting that CD74 may play a critical role in generation and maintenance of cancer stem cells (CSC) via regulating the function of CD44." (PMID 27626171, 2016). "Lymphocytes expressing CD44 and CD25 in the spleen were downregulated with an increase in CD44loCD25− lymphocytes, suggesting that TT treatment may reduce inflammation as seen by the decrease in circulating, activated T-lymphocytes induced by the mouse mammary carcinoma cells." (PMID 26113869, 2015). "Down-regulation of CD44 decreased the rate of onset and the magnitude of tumor burden in the animals, at all clinically-relevant sites including the brain, lung, liver and skeleton, indicating that CD44 does not preferentially select for the metastasis of breast cancer cells to specific tissues." (PMID 25888636, 2015). "In addition, we also discovered that VCAM-1 activation was involved in the development of chemoresistance in NMuMG breast cancer cells after exposure to low-dose doxorubicin in vitro, and VCAM-1 may contribute to the activation of CD44 and ABCG2 pathways in NMuMG and MDAMB231 cells." (PMID 24583847, 2014). "Since exon v10 localizes in the ectodomain of CD44 and reagents such as antibodies and DNA aptamers inhibited migration of HCC38 cells, we hypothesized that CD44 forms a molecular complex with other cell surface molecules which promotes migration of TN breast cancer cells." (PMID 24586375, 2014). "Interestingly, further studies have shown that CD44 can act to limit drug sensitivity in prostate cancer cells and in clinical ovarian cancer but a relationship between CD44 and endocrine response in breast cancer has not yet been reported." (PMID 23039365, 2012).
breast carcinoma (continued). "All sphere and monolayer derivative cell models investigated in this report exhibit a unique CD24−/CD44+ marker distribution, although only the S2N spheres were highly tumorigenic at low inoculation cell numbers in vivo (confirmed in 2 more primary breast cancer cell models, data not shown)." (PMID 23042145, 2012). "Additionally, using a fluorescent assay that was reported to sort putative CSC from lung cancer, breast cancer, and multiple myeloma on the basis of differential ALDH activity, a small fraction of the MPE-derived primary tumors displayed the ALDHhi/CD44+ phenotype." (PMID 19536353, 2009). "Because the percentage of CD44+/CD24- cells in breast cancer cell lines does not predict tumorigenic potential, we next considered whether adding ESA to the repertoire of cell surface markers could enrich for tumor initiation capacity, as was previously demonstrated." (PMID 18366788, 2008). "Cells that are CD44 positive and CD24 negative or low are generally considered to have stem cell-like properties in breast cancer." (PMID 39955575, 2025). "Before investigating the antitumor activity of CRAd-synNotch and ADX730 in T24 (MIBC) and BT474 (a COX-2 negative human breast cancer cell line) cells, we confirmed the expressions of CAR, CD46 and CD44 expressions on the cell surface." (PMID 40011711, 2025). "Previously, we found that in breast cancer, CTCs with phenotypes including co-expression of the epithelial marker CK7/8 and the stemness marker CD133, but not CD44+/CD24−, were more characterized by a lack of evidence of apoptosis." (PMID 39456890, 2024). "In agreement with previous data, the proportions of CD44+CD24- and ALDH1+ breast CSCs were dramatically increased among breast cancer cells cocultured with CCL18-activated NBFs but not with treatment-naive or TGF-β-treated NBFs." (PMID 36418470, 2023). "It has also been demonstrated that PD-L1 was highly expressed on CD44+ CSCs compared to CD44− non-CSCs in head and neck squamous cell carcinoma (HNSCC) and regulates stemness in breast cancer." (PMID 36900399, 2023). "Compared to non-stem cells, CD44+CD24−/low cells from MCF-7, MDA-MB-231, and SK-BR-3 breast cancer cell lines showed higher expression of ABCG2." (PMID 35563449, 2022). "Of note, nontumorigenic MCF-7 breast cancer cells became tumorigenic and metastatic upon fusion with M2-macrophage-like U937D2 cells, gained a CD44+CD24−/low phenotype, and overexpressed epithelial–mesenchymal-transition-associated genes." (PMID 35562905, 2022). "For instance, high expression of CD44 and low expression of CD24 (CD44+/CD24−/low) together with expression of ALDH1 is a feature of breast cancer stem cells as compared to non-stem breast cancer cells." (PMID 35456011, 2022). "In this study, we discovered both membrane and nonmembrane protein targets of MARCH8, i.e., CD44 and signal transducer and transcription activator 3 (STAT3), respectively, in different subtypes of breast cancer cells." (PMID 34067416, 2021). "The stem-like population of cells in breast cancer is characterised by high expression of CD44 and low or no expression of CD24 (CD44+/CD24-)." (PMID 34863149, 2021). "Analyzing the expression of breast cancer stem cell markers CD44 and CD24, we found that over 95% of control MDA-MB-231 cells express CD44 but not CD24, thus exhibiting a breast cancer stem-like cell phenotype." (PMID 34725457, 2021). "Liu and colleagues isolated CSCs (using ESA+/CD24−/CD44+/lin− CSC and ESA+/CD24+/CD44−/lin− non-CSC markers) from six breast cancer tissue samples and identified any changes in the miRNAs by miRNA microarray." (PMID 33916548, 2021). "Detailed analysis revealed that CD44+/CD24−/low and ALDH1 biomarkers identified largely nonoverlapping cell populations in primary human breast cancers." (PMID 33327542, 2020).
breast carcinoma (continued). "Herein, We used Immunohistochemistry to characterize CD44 expression levels on the surface of MCF-7 and BT-20 breast cancer cells, as shown in proved that MCF-7 was negative CD44, while BT-20 showed positive CD44." (PMID 32151062, 2020). "Our results show a positive correlation between BRCA1 and CD44, HAS2, HAS3 and HYAL1 in colorectal but not breast cancer." (PMID 32610620, 2020). "Data from over 100 breast cancer patients who underwent neoadjuvant chemotherapy with paclitaxel and epirubicin suggest that ALDH1+ cells, but not CD44+CD24− cells, contribute to resistance against chemotherapy." (PMID 30733805, 2019). "While exposing these mesenchyme-like breast cancer cells to GSK3β inhibitors increased CD24 expression, we did not see any change in the CD44 expression." (PMID 30845991, 2019). "We measured the SUV420H2 mRNA and protein levels in MCF-7 cells, MCF-7 spheroid cells, CD44+/CD24− MCF-7 cells, MDA-MB-231 cells and in breast cancer tissues compared to their corresponding distal non-cancerous tissues." (PMID 30792382, 2019). "Histopathological analyses of breast cancer patient tissues have revealed that compared to non-TNBC tissues, TNBC tissues exhibit enriched ALDH1 and CD44+/CD24− expression signatures." (PMID 31324052, 2019). "In FMC and human breast cancer cell lines, CSCs express high levels of CD133, CD44 and low (or none) CD2430,68,69." (PMID 30185896, 2018). "Our previous investigation of benign mammary stroma indicated that low presence of ALDH1+ CD44+ CD24– r/o cells in premenopausal women is marginally correlated with a family history of breast cancer, but that this does not apply to ALDH1+ CD44– CD24– cells." (PMID 29486751, 2018). "Unlike in breast cancers, we identified a significant overlap between the ALDH+ and CD44+CD24− populations, with substantial interindividual variation in the degree of overlap." (PMID 29606612, 2018). "We also repeated the assays in the SCP28 breast cancer cell line and found that ESRP1 overexpression also led to CD44 isoform switching and elevation of lung metastasis, but not affecting the CSC feature of the cells." (PMID 28300837, 2017). "Here we found that the CD44/CD24 ratio and the expression of ALDH1 were not consistent in the breast cancer, suggesting their different origins and properties." (PMID 29062075, 2017). "For the first time, breast cancer-initiating cells were isolated based on the expression of unique cell surface antigens, which include epithelial specific antigen (ESA) and CD44, but not CD24." (PMID 29258583, 2017). "Although about 10-20% of breast cancers are triple negative, it would be of interest to study CD74 and CD44 in a cohort of breast cancer cells tested negative for estrogen receptors, progesterone receptor, and HER2." (PMID 29190904, 2017). "Further investigation indicates that these breast cancer tumors contain a subpopulation of highly tumorigenic cancer stem cells (CSCs) characterized by high CD44 expression and low (or no) CD24 expression (CD44+CD24−/low)." (PMID 27070574, 2016). "Using 51 different breast cancer cell lines, we found that TNBC cell lines exhibit higher expression of the cancer stem cell surface marker CD44 and lower expression of the non-CSC CD24 compared with other subtypes." (PMID 27759034, 2016). "Inoculation of small numbers of CD44+/CD24−/low breast cancer cells in NOD/SCID mice can recapitulate the phenotypic heterogeneity of the parent tumor, whereas cells lacking the CD44+/CD24−/low marker have a greatly reduced tumor-forming capacity." (PMID 25686831, 2015). "Although CD44+/CD24− and ALDH+ as the most often used molecular markers for breast CSCs, not all breast cancer cell lines contain CSCs equivalently expressing these markers." (PMID 25612916, 2015).
breast carcinoma (continued). "To ascertain the functional importance of CD44 in the context of estrogen receptor negative breast cancers, we used the CD44-expressing MDA-MB-231 cell line, which retains the CD44+/CD24−/low phenotype characteristic of tumor-initiating breast cancer cells." (PMID 25888636, 2015). "A number of potential markers of breast cancer stem cells have been identified (CD44+CD24−, ALDH1+), but these do not universally mark breast cancer stem cells, with variation evident between individual tumors." (PMID 25849559, 2015). "It was clear, however, that the CD44+CD24-/low surface markers enrich for tumorigenic cells in some, but not all, breast cancers." (PMID 25928070, 2014). "Nevertheless, in certain breast cancer patients, CD44+/CD24- cells are still sensitive to radiotherapy, suggesting that not all breast CSCs are radioresistant and that not all CD44+/CD24- cells are CSCs." (PMID 23799994, 2013). "In concordance to our findings in breast cancer cell lines, primary cancer tissues of triple negative breast cancer had higher frequency of ALDH+ and CD44+CD24- cells." (PMID 23883436, 2013). "CD44 (isoform 10) was found to be selectively packaged in the breast cancer-derived DXMP relative to its donor cells, where surprisingly no CD44 was detected by Western blot." (PMID 23593486, 2013). "We therefore investigated the relationship between CD44 and hypoxia in triple (estrogen receptor, progesterone receptor and Her2/neu) negative (ER, PR, Her2/neu negative) MDA-MB-231 and SUM-149 human breast cancer cells." (PMID 22937154, 2012). "In breast cancer, the in vivo inoculation of low cell numbers of CD24−/CD44+ but not CD24+/CD44+ or ESA-purified cells from primary tumors gave rise to xenograft tumors." (PMID 23042145, 2012). "Regardless of the positivity or negativity of CD44 and CD24, the cells expressing these markers in breast cancer were highly acknowledged with invasive properties but lacking metastatic genes." (PMID 22693526, 2012). "Whereas breast cancer cell lines without CD44+/CD24- cells lacked invasive capacity, those with CD44+/CD24- subpopulation (MDA-MB-231, MDA-MB-436, and Hs578T) exhibited invasion." (PMID 17062128, 2006). "CD44+/CD24-/Lin- cells from primary breast cancers progress to CD44+/CD24+, CD44-/CD24+, and CD44-/CD24- phenotypes when implanted into mammary fat pad of nonobese diabetic/severe combined immunodeficiency mice." (PMID 17062128, 2006). "To assess the prognostic role of the EpCAM-CK7/8-CD24+ population, since CD44 expression was not relevant, we combined CD44- and CD44+ subpopulations of CCs and further evaluated the differences of EpCAM-CK7/8-CD24+N-cadherin- CCs in M0 and M0mts breast cancer patients." (PMID 38806508, 2024). "A transient knockdown of ESRP1 in human breast cancer MCF7 and human pancreatic adenocarcinoma BxPC-3 cells resulted in a shift of expression from CD44v (containing exon v6) to CD44 isoform 4 without affecting total CD44 level." (PMID 38106992, 2023). "In addition, analysis of the GEO database for breast cancer patients showed a positive correlation between GPR110 expression and CD44 gene and a negative correlation between GPR110 expression and CD24 gene." (PMID 35614051, 2022). "We found that p97 was consistently at a higher level in the CD44+/CD24−, ALDH+, or PKH26+ CSC populations than the respective non-CSC populations in human breast cancer tissues and cancer cell lines and p97 expression also positively correlated with that of SOX2, another CSC marker." (PMID 33731668, 2021).